SCO2 (synthesis of cytochrome C oxidase 2)
Diseases named in the same sentence as SCO2 in open-access papers:
SCO2 is named in the same sentence as 53 diseases in open-access papers, as found by Europe PMC text mining. Sharing a sentence is not in itself a finding about the gene and the disease. The quoted sentences say what the papers report.
Leigh syndrome (7 papers, 2018 to 2025). "Owing to the severity of cardiomyopathy and/or Leigh disease, most cases of SCO2 mutations reported so far exhibited an early onset and a rapidly fatal course." (PMID 31844624, 2019). "Furthermore, mutations in the SCO2 gene result in cytochrome c oxidase deficiency, causing symptoms such as Leigh syndrome, hypertrophic cardiomyopathy, lactic acidosis, ventilator insufficiency, and a phenotype similar to SMA." (PMID 39815358, 2025). "SCO2 is highly conserved in a wide variety of species across prokaryotes and eukaryotes, and mutations in SCO2 are known to cause mitochondrial diseases such as fatal infantile cardioencephalomyopathy, Leigh syndrome, and Charcot-Marie-Tooth disease, a neurodegenerative disorder." (PMID 34707123, 2021). "Pathogenic variants in the SCO2 gene (OMIM*604272; NM_005138.3) were found in 9.6% of Leigh syndrome cases in the Russian Federation." (PMID 36675121, 2023). "For example, SURF 1 (Leigh-syndrome), SCO2 (hypertrophic cardiopathy), SCO1 (hepatic failure) and COX 10 (sensorineural hearing loss, anemia, and hypertrophic cardiomyopathy)." (PMID 30223867, 2018).
breast carcinoma (6 papers, 2015 to 2024). "Thus, we conclude that HBXIP promotes the growth of breast cancer cells through miR-183/96/182 targeting SCO2 and PDHA1 in vivo." (PMID 26309161, 2015). "We identified 13 members of the copper transport system associated with the occurrence, progression, and mortality of breast cancer, including SLC31A1, DMT1, ATP7A, ATP7B, MTs, GSH, ATOX1, CCS, COX17, SCO1, SCO2, and COX11." (PMID 39676279, 2024). "In breast cancer, HBXIP can enhance glucose metabolism reprogramming through suppressing SCO2 and PDHA1." (PMID 28388957, 2017). "Based on the notion that miR-183/96/182 cluster inhibited the expression of SCO2 and PDHA1 through targeting SCO2 and PDHA1 mRNA CDSs, we further evaluated the effect of miR-183/96/182 on the glucose metabolism reprogramming in breast cancer cells." (PMID 26309161, 2015). "Our data showed that miR-183/96/182 cluster was able to downregulate the expression of SCO2 and PDHA1 in breast cancer cells at the post-transcriptional level." (PMID 26309161, 2015). "The downregulation of SCO2 and PDHA1 leads to the increase of lactate production and intracellular glucose, and the decrease of ROS, promoting the growth of breast cancer cells." (PMID 26309161, 2015). "Our data show that HBXIP promotes the glucose metabolism reprogramming through downregulating SCO2 and PDHA1 in breast cancer cells, involving HIF1α/miR-183/96/182 cluster/pVHL signaling." (PMID 26309161, 2015). "Accordingly, we validated that HBXIP was able to downregulate the expression levels of SCO2 and PDHA1 in breast cancer cells." (PMID 26309161, 2015). "Overall, we conclude that HBXIP regulates the glucose metabolism reprogramming and downregulates SCO2 and PDHA1 in breast cancer." (PMID 26309161, 2015). "Next, we try to identify the mechanism by which HBXIP downregulates SCO2 and PDHA1 in breast cancer cells." (PMID 26309161, 2015). "Therefore, we conclude that miR-183/96/182 cluster is able to downregulate the expression of SCO2 and PDHA1 at the post-transcriptional level in breast cancer cells." (PMID 26309161, 2015). "It suggests that the miR-183/96/182 cluster might be involved in the glucose metabolism reprogramming through targeting SCO2 and PDHA1 in breast cancer cells." (PMID 26309161, 2015). "According to above observation that HBXIP downregulates SCO2 and PDHA1 which are targeted by miR-183/96/182, we are interested in whether HBXIP is able to upregulate miR-183/96/182 in breast cancer cells." (PMID 26309161, 2015).
axonal neuropathy (2 papers, 2020 to 2024). Any nerve disorder affecting the axon of a nerve. "Over the last years, some authors reported purely axonal neuropathy associated with less severe mutations in other “mitochondrial genes”, e.g. for SCO2 or MTATP6." (PMID 38217609, 2024). "Mitochondrial diseases often present with fatal infantile phenotypes but over the last years some authors reported isolated axonal neuropathy phenotypes, e.g. for SCO2 and MTATP6." (PMID 38217609, 2024). "Interestingly, mutation of another gene with similar copper-binding functions, SCO2, was reported to cause a different type of axonal CMT with similar symptoms, thus highlighting the possible role of copper homeostatic imbalance in axonal neuropathy." (PMID 32294113, 2020).
autism (1 paper, 2012). Persistent deficits in social interaction and communication and interaction as well as a markedly restricted repertoire of activity and interest as well as repetitive patterns of behavior.
bladder cancer (1 paper, 2025). "In cisplatin-resistant bladder cancer cell lines, FLRT2, HOXC5, SCD, GRM7, HMGA1, ETV7, and SCO2 were highly expressed, while EMP1, SERPINA6, and ZNF124 exhibited lower expression levels." (PMID 39744172, 2025).
cardiomyopathy (1 paper, 2017). A disease of the heart muscle or myocardium proper. "In humans, Sco1 and Sco2 gene mutations resulting in cytochrome C oxidase (COX) deficiency are associated with cardiomyopathy." (PMID 27904993, 2017). "In Sco2 knockout mice apoptosis is increased in the muscle and liver, strongly implicating cell death in COX deficiency-associated cardiomyopathy caused by Sco gene mutations in humans." (PMID 27904993, 2017).
colon cancer (1 paper, 2011).
colorectal adenocarcinoma (1 paper, 2022). The most common type of colorectal carcinoma. "In the second step, we took advantage of the human colorectal adenocarcinoma cell line HCT116 SCO2 KO, in which the mitochondrial complex IV assembly SCO2 gene is depleted." (PMID 36408232, 2022).
colorectal cancer (1 paper, 2022). A primary or metastatic malignant neoplasm that affects the colon or rectum. "In our studies, the human colorectal cancer cell line HCT116 SCO2 KO is deficient in the mitochondrial complex IV assembly SCO2 gene." (PMID 36408232, 2022).
COVID-19 (1 paper, 2025). A disease caused by infection with severe acute respiratory syndrome coronavirus 2. "The ODF3B (ciliary microtubule associated protein 1B)–SCO2 (synthesis of cytochrome c oxidase 2) (OS) and TYMP (thymidine phosphorylase)-SCO2 (TS) chimeric isoforms made up the majority of the 14 chimeras found only in the PTBP1 knockdown and COVID-19 samples." (PMID 40110491, 2025).
cytochrome c oxidase deficiency (1 paper, 2016). "Mouse models of early-onset LS caused by cytochrome c oxidase deficiency have been developed previously by knocking out or knocking in a mutation in the gene Sco2, encoding an assembly factor of complex IV26, to understand the pathology of this disease." (PMID 27319982, 2016).
demyelinating peripheral neuropathy (1 paper, 2021). "As mutations in SCO2, a mammalian homolog of Scox, cause CMT type 4, which is a group of demyelinating peripheral neuropathy, perturbation of SCO2 in glial cells may play an essential role in the pathogenesis of CMT." (PMID 34707123, 2021).
Dystonia (1 paper, 2024). An abnormally increased muscular tone that causes fixed abnormal postures. "There have been reports suggesting that mutations in the SURF1, COX20, and SCO2 genes, which are involved in the assembly of COX along with COA7, can result in a decrease in the activity of MRC complex IV, leading to dystonia or parkinsonism." (PMID 37750949, 2024).
Insulin resistance (1 paper, 2022). Increased resistance towards insulin, that is, diminished effectiveness of insulin in reducing blood glucose levels. "Mutations and knockout of SCO2 have been implicated in fatty acid processing and insulin resistance in mouse models, further implicating mitochondrial copper dysfunction in fat accumulation." (PMID 35480878, 2022).
metabolic syndrome (1 paper, 2022). A cluster of metabolic risk factors for CARDIOVASCULAR DISEASES and TYPE 2 DIABETES MELLITUS. "Mutations in genes encoding cytochrome c oxidase (mitochondrial complex IV) subunits and assembly factors [e.g., synthesis of cytochrome c oxidase 2 (SCO2)] are linked to severe metabolic syndromes." (PMID 35302710, 2022).
metastatic tumors (1 paper, 2016). "However, we found that the SCO2 gene was frequently amplified in metastatic tumors and these alterations corresponded to the mRNA levels of SCO2." (PMID 26725848, 2016). "However, 6 genes were amplified at significantly higher frequencies in metastatic tumors: SCO2 (p = 1.1 × 10−9), MLXIPL (p = 2.1 × 10−4), PPARA (p = 1.2 × 10−10), PPARD (p = 4 × 10−15), CAV1 (p = 3.4 × 10−4) and CD36 (p = 3.5 × 10−4)." (PMID 26725848, 2016).
neuropathies (1 paper, 2024). "Recently, we successfully applied proteomic profiling on white blood cells to address the pathogenicity of a new SCO2 variant associated with neuropathy and obtain new insights into the underlying pathophysiology." (PMID 38217609, 2024). "However until this approach will become the standard diagnostic test we recommend that NDUFS6 together with other mitochondrial genes (including SCO2 and SURF1) should be included in panels for molecular genetic testing of neuropathies, intellectual disabillity and optic atrophy." (PMID 38217609, 2024).
ovarian carcinoma (1 paper, 2025). A malignant neoplasm originating from the surface ovarian epithelium. "Following the knockdown of LRPPRC in two ovarian cancer cell types, we observed a reduction in the expression of chaperone proteins SCO1 and SCO2, with a more pronounced decrease in SCO1." (PMID 41516324, 2025).
prostate carcinoma (1 paper, 2023). A carcinoma that arises from epithelial cells of the prostate gland. "In this section, we attempted to clarify how cell density affects OXPHOS in prostate cancer cells by examining the mRNA expression levels of two OXPHOS-related genes, synthesis of cytochrome c oxygenase 2 (SCO2) and pyruvate dehydrogenase kinase 1 (PDK1)." (PMID 36919762, 2023).
psoriasis (1 paper, 2025). An autoimmune condition characterized by red, well-delineated plaques with silvery scales that are usually on the extensor surfaces and scalp. "In addition, 8 genes (DEFB103A, OASL, HERC6, ISG15, MKI67, MX1, MXD1, SCO2) were considered to have statistically significant differences in sensitivity of short-term treatment for psoriasis." (PMID 40560938, 2025).
renal adysplasia (1 paper, 2022). "The SULT4A1, PARVB, SCO2, and UPK3A genes are associated with neurological features, macrocephaly/hypotonia, oculopathy, and renal adysplasia, respectively." (PMID 36118903, 2022).
retinal dystrophies (1 paper, 2022). "Furthermore, 24 families had VUS, two families with variants in genes related to non-syndromic EoHM (SCO2 and ZNF644) and seven families with variants in genes associated with other retinal dystrophies (TRPM1, CACNA1F, KCNV2, RDH5 and MERTK)." (PMID 35457050, 2022).
systemic juvenile idiopathic arthritis (1 paper, 2014). "Notably, the relevant genes, which include the ATP6, SCO2, CYTB, DN1, COX1, ANT1, are mainly function in oxidative phosphorylation, whereas dysfunction in oxidative phosphorylation related genes is closely related to the systemic juvenile idiopathic arthritis and endemic osteoarthritis." (PMID 24551036, 2014).
cancer (8 papers, 2011 to 2025). A tumor composed of atypical neoplastic, often pleomorphic cells that invade other tissues. "On basis of the existing literature and the cellular outcomes observed upon upregulation of TIGAR and SCO2 in cancer cells, the cellular conditions which might lead to the synthesis of these genes can be predicted." (PMID 22248668, 2011). "In addition, these miRNAs may also target key regulators of glucose metabolism, such as synthesis of cytochrome C oxidase 2 (SCO2) and pyruvate dehydrogenase alpha 1 (PDHA1), in favor of cancer progression." (PMID 37583933, 2023). "In addition, these miRNAs may also target SCO2 and PDHA1 and promote glucose metabolism in favor of cancer progression." (PMID 37583933, 2023).
tumor (8 papers, 2015 to 2025). "Furthermore, we validated the effect of HBXIP on PDHA1, SCO2 or HIF1α in xenograft tumor tissues by Western blot analysis and IHC analysis, respectively." (PMID 26309161, 2015). "Therefore, in these patient samples, in addition to the induction of genes related to cell cycle arrest (p21), DCA also stimulated tumor cell metabolism by promoting the expression of AMPKβ1, GLS2 and SCO2." (PMID 26231043, 2015).
mitochondrial disease (6 papers, 2013 to 2024). "Eight patients were diagnosed with inborn errors of metabolism (IEM), especially mitochondrial diseases (seven patients) and among them were three patients with SCO2 gene variants." (PMID 32668698, 2020). "Along this line, peripheral neuropathy as the leading symptom has already been reported in patients with mutations in some other primary mitochondrial disease genes (e.g. SCO2, SURF1) which are commonly associated with much more severe clinical presentations or even early death." (PMID 38217609, 2024). "Following that, a thorough discussion is included based on the mitochondrial genetic disorders that are attributed mainly to genetic mutations/pathogenic variants affecting the structure and functions of the mitochondrial protein Sco2 that lead to both severe Sco2 deficiency and COX deficiency." (PMID 36678915, 2023). "In a total of 148 patients we analyzed, there was only one additional gene SCO2 in the category of primary mitochondrial disease causative genes, with variants that we classified as of unknown significance as we did not receive parental samples, but most likely associated with disease." (PMID 24215330, 2013). "Like our results, one study using the genetic mitochondrial disease mouse model (Sco2 knockout/knock-in model) found that NR supplementation improved the mutant's exercise capacity whereas their control group gained no benefits." (PMID 36107830, 2022).
cardiac diseases (1 paper, 2025). "Among 244 genes associated with cardiac diseases, three candidate variants with high confidence of pathogenicity were identified in the UTRs of SCO2, CALM2 and TBX3 based on a rigorous filtering strategy." (PMID 39266800, 2025).
SCO2 also shares sentences with these, for which no sentence is quoted: myopia (7 papers); Charcot-Marie-Tooth disease (2); fatal infantile cardioencephalomyopathy (2); hypertrophic cardiomyopathy (2); anemia (1); bladder tumor (1); encephalomyopathies (1); Hepatic failure (1); hepatoma (1); inborn errors of metabolism (1); intellectual impairment (1); Juvenile glaucoma (1); Knobloch syndrome (1); lactic acidosis (1); learning disabilities (1); lipid storage myopathy (1); Marfan syndrome (1); optic atrophy (1); OXPHOS disease (1); Parkinsonism (1); peripheral neuropathy (1); respiratory failure (1); sensorineural hearing loss (1); Stickler syndrome type 1 (1); Stickler syndrome type 2 (1); Stickler syndrome type 3 (1).